ALDH1A3 (aldehyde dehydrogenase 1 family member A3)
Description:
Catalyzes the NAD-dependent oxidation of aldehyde substrates, such as all-trans-retinal and all-trans-13,14-dihydroretinal, to their corresponding carboxylic acids, all-trans-retinoate and all-trans-13,14-dihydroretinoate, respectively (By similarity). High specificity for all-trans-retinal as substrate, can also accept acetaldehyde as substrate in vitro but with lower affinity. Required for the biosynthesis of normal levels of retinoate in the embryonic ocular and nasal regions; a critical lipid in the embryonic development of the eye and the nasal region (By similarity).
Synonyms: RalDH3; ALDH6; ALDH1A6; MCOP8
Tractability: Small molecule: a structure with a bound ligand is known; a high-quality ligand is known; it belongs to a druggable protein family. PROTAC: ubiquitination databases record sites on it; a small molecule that binds it is known.
Target class: Enzyme; Oxidoreductase
Gene: Protein-coding gene on chromosome 15 (100,861,924 to 100,916,628, forward strand). Ensembl gene ENSG00000184254.
Subcellular location: Cytoplasm
Subcellular location (Human Protein Atlas): Nucleoplasm; Cytosol
Pathways (Reactome):
Developmental Biology: Developmental Lineage of Mammary Gland Alveolar Cells; Developmental Lineage of Mammary Gland Luminal Epithelial Cells; Developmental Lineage of Mammary Gland Myoepithelial Cells; Developmental Lineage of Mammary Stem Cells
Signal Transduction: RA biosynthesis pathway
Gene Ontology:
Molecular function: aldehyde dehydrogenase [NAD(P)+] activity; NAD+ binding; protein homodimerization activity; retinal dehydrogenase (NAD+) activity; aldehyde dehydrogenase (NAD+) activity; oxidoreductase activity; thyroid hormone binding
Biological process: protein homotetramerization; retinal metabolic process; retinoic acid biosynthetic process; retinoic acid metabolic process; 9-cis-retinoic acid biosynthetic process; aldehyde metabolic process; embryonic camera-type eye development; embryonic eye morphogenesis; Harderian gland development; nose development; retinol metabolic process
Cellular component: cytoplasm; cytosol; extracellular exosome; nucleoplasm
Genetic constraint (gnomAD): Loss-of-function variants: 26 observed, 54.12 expected, observed/expected ratio (o/e) 0.48, 90% interval 0.35 to 0.67. The upper end of that interval is the gene's LOEUF score, 0.67, which puts it in group 2 of 6, group 1 being the genes least tolerant of losing a copy. Missense variants: 502 observed, 661.06 expected, observed/expected ratio (o/e) 0.76, 90% interval 0.7 to 0.82. Synonymous variants: 280 observed, 266.42 expected, observed/expected ratio (o/e) 1.05, 90% interval 0.95 to 1.16.
Homologues: Orthologues: chimpanzee ALDH1A3 (99% identical), macaque ALDH1A3 (98% identical), pig ALDH1A3 (95% identical), mouse Aldh1a3 (94% identical), rat Aldh1a3 (94% identical), dog ALDH1A3 (93% identical), tropical clawed frog aldh1a3 (81% identical), zebrafish aldh1a3 (70% identical). Paralogues in human: ALDH1A2 (70% identical), ALDH1A1 (68% identical), ALDH2 (65% identical), ALDH1B1 (62% identical), ALDH1L2 (48% identical), ALDH1L1 (47% identical), ALDH8A1 (36% identical), ALDH9A1 (35% identical), ALDH5A1 (34% identical), ALDH6A1 (31% identical), ALDH7A1 (30% identical), ALDH4A1 (27% identical), and 5 more.
Diseases named in the same sentence as ALDH1A3 in open-access papers:
ALDH1A3 is named in the same sentence as 132 diseases in open-access papers, as found by Europe PMC text mining. Sharing a sentence is not in itself a finding about the gene and the disease. The quoted sentences say what the papers report.
breast carcinoma (87 papers, 2012 to 2026). "ALDH1A1 and ALDH1A3 both drive retinoic acid production in breast cancer, and have been linked to angiogenesis, tumor invasion, and metastasis." (PMID 40076923, 2025). "Together, these findings identify ALDH1A3 as a key regulator of processes required for breast cancer progression and depletion of ALDH1A3 makes breast cancer cells more susceptible to glycolysis inhibition." (PMID 39251846, 2024). "ALDH1A3's effects on breast cancer progression and gene expression have also been linked to its production of ATRA." (PMID 37753740, 2024). "Together this data suggests there are potential associations with ALDH1A3 with hybrid phenotypes and/or its modulation of cells factors associated with hybrid phenotypes within the breast cancer cell lines." (PMID 39251846, 2024). "In breast cancer patient tumour tissues, ALDH1A3 and tPA were significantly co‐expressed and associated with features of aggressive disease." (PMID 37753740, 2024). "Breast cancer with lymph node metastases were in general associated with lower levels of the CSC genes ALDH1A3 and CD44, pluripotency markers POU5F1 and NEAT1, EMT marker SLUG, and drug resistance associated gene ERBB2, after DOX treatment." (PMID 38124067, 2023). "ALDH1A3 overexpression significantly increased ALDEFLUOR activity in MDA-MB-231 breast cancer cells, and the increase was greater than that caused by ALDH1A1 overexpression." (PMID 36651035, 2023). "In breast cancer, patient tumors with high levels of ALDH1A3 were associated with an increased incidence of metastasis compared to those with low levels of ALDH1A3." (PMID 36672441, 2023). "In 2011, the then little-studied aldehyde dehydrogenase 1A3 (ALDH1A3) enzyme in the context of cancer, was shown to generate the high Aldefluor activity associated with breast cancer stem cells (CSCs)." (PMID 36672441, 2023). "The up-regulation of retinoic acid (RA) signalling by ALDH1A3 can cause breast cancer growth, and citral inhibited the expression of RA-inducible genes mediated by ALDH1A3." (PMID 35052524, 2021). "Enhanced ALDH activity is a hallmark of normal and cancer stem cells, and ALDH1a3 activity, in particular, significantly contributes to the Aldefluor positive phenotype in mouse hematopoietic stem cells and human breast cancer CSC53." (PMID 27292795, 2016). "Other ALDH isoforms have been mechanistically associated with metastatic behavior in vitro, including ALDH1A3 in breast cancer, melanoma, pancreatic cancer and brain cancer; ALDH3A1 in prostate cancer and liver cancer; and ALDH7A1 in prostate cancer." (PMID 26445849, 2016). "Overall, the staining of fixed breast cancer patient tumours suggests that among these four proteins, ALDH1A3 has the strongest associations with the TNBC subtype, higher tumour grade, and later recurrence (progression) and that tPA has similar associations that overlap with ALDH1A3." (PMID 37753740, 2024). "NRAD1 may be a cause of at least some of the stemness and tumorigenicity associated with ALDH1A3 in breast cancer, as its knockdown reduced tumor growth and mammosphere formation potential." (PMID 36672441, 2023). "In addition, the observation that ALDH1A3 knockdown only caused a 50% reduction in ALDH activity suggests that other ALDH isozymes must be involved in Aldefluor® activity in breast cancer cells." (PMID 28937653, 2017). "Both ALDH1A1 and ALDH1A3 have been associated with poor prognosis in breast cancer." (PMID 24887554, 2014). "As an important DUB, USP9X regulates multi-types of cancer development, such as glioblastoma, lung cancer, colorectal cancer, and breast cancer, through mediating the stability of ALDH1A3, KDM4C, FBW7, CEP131, and Snail1." (PMID 40246814, 2025). "Given its involvement in various pathological conditions including breast cancer, glioblastoma, and epithelial ovarian cancer, ALDH1A3 has emerged as a compelling target for the development of novel therapeutic agents and as a potential prognostic biomarker." (PMID 40887554, 2025).
breast carcinoma (continued). "Integrated metabolomic and transcriptomic profiling in breast cancer has identified ALDH1A3 as a definitive cancer stem cell (CSC) marker, strongly associated with tumor initiation, therapy resistance, and metastatic potential." (PMID 40900801, 2025). "The ALDH1A3 isoform has been reported to be highly expressed in breast cancer, and mesenchymal glioma stem-like cells (GSCs)." (PMID 40887554, 2025). "Overall, these results are consistent with 2DG inhibiting the effects on EMT induced by ALDH1A3 in breast cancer." (PMID 39251846, 2024). "Consistently, we noted generally similar co‐expression of these genes with ALDH1A3 in hormone receptor+ breast cancers, normal adjacent tissues and TNBC cell lines." (PMID 37753740, 2024). "ALDH1A3 reduction rendered the breast cancer cells vulnerable to glycolysis inhibition with inhibitor 2-deoxy-D-glucose (2DG), which reduced the increased CD24−CD44+ population, migration, ROS, glycolysis, tumor growth, and tumor initiation potential." (PMID 39251846, 2024). "We next assessed if the gene expression changes in CDH1 and CDH2 induced by ALDH1A3 in the breast cancer cells translate to protein changes in the cells." (PMID 39251846, 2024). "In our previous work on the mechanisms of ALDH1A3 in breast cancer, we found that DNA methylation of ALDH1A3/ATRA inducible genes plays a major role on in if a gene can be induced by ALDH1A3/ATRA." (PMID 37753740, 2024). "Here we found that ALDH1A3 induces a mixed EMT/MET phenotype in breast cancer cells that have increased invasion but decreased migration." (PMID 39251846, 2024). "This study provides a comprehensive exploration of ALDH1A3’s multifaceted impact on breast cancer, elucidating its roles in CSC maintenance and tumor heterogeneity, EMT and MET, and metabolic reprogramming." (PMID 39251846, 2024). "We next investigated if 2DG affects the expression of EMT/MET genes altered by ALDH1A3 in the breast cancer cells." (PMID 39251846, 2024). "While ALDH1A3 increases ALDH+ breast cancer cells, it inversely suppresses the CD24−CD44+ population by retinoic acid signaling-mediated gene expression changes." (PMID 39251846, 2024). "We therefore knocked down ALDH1A3 in MDA-MB-468 and HCC1806 cells and overexpressed ALDH1A3 in MDA-MB-231 cells to study the effects of the enzyme in the breast cancer cells." (PMID 39251846, 2024). "In the TCGA BRCA and METABRIC breast cancer patient tumor datasets, patient tumors with high ALDH1A3 had higher EMT scores, with mean EMT scores closer to neutral." (PMID 39251846, 2024). "For example, expression of CD44, CD24, and ALDH1A3 can quantify epithelial and mesenchymal stem cell states in breast cancer and normal breast tissue." (PMID 38915368, 2024). "The ALDEFLUORTM kit used to isolate CSCs in this study has previously been shown to select cells expressing high levels of ALDH1A1, ALDH3A1, ALDH1A3 and ALDH2 isoforms, which are closely linked to breast cancer stem cells." (PMID 39768151, 2024). "In breast cancer, elevated ALDH1 expressions, particularly ALDH1A1 and ALDH1A3, are associated with chemoresistance, particularly cyclophosphamide-based regimens." (PMID 39796106, 2024). "ALDH1A3 decreases aerobic glycolysis and lactate production while increasing ATP synthase activity of oxidative phosphorylation in breast cancer cells." (PMID 39251846, 2024). "In terms of inhibiting the ALDH1A3 isoform specifically, disulfiram has minimal ALDH1A3 targeting activity in breast cancer cells and inhibited glioblastoma stem cells independent of effects on ALDH1A3." (PMID 36672441, 2023). "Bladder cancer, breast cancer, and intrahepatic cholangiocarcinoma were shown to have increased ALDH1A3 expression along with high tumor stage." (PMID 36672441, 2023). "For breast cancer, gene expression analysis and knockdown of the 19 ALDH isoforms revealed that ALDH1A3 expression was the primary isoform contributing to Aldefluor activity of breast cancer patient tumors and cell lines." (PMID 36672441, 2023).
breast carcinoma (continued). "In breast cancer, ALDH1A3 imparted increased colony formation to TNBC MDA-MB-231 and MDA-MB-468 cells." (PMID 36672441, 2023). "And in TNBCs and basal‐like subtypes, cancer cells have higher levels of ALDH1A3 expression, implying the prognostic value of ALDH1A3 in breast cancer patients." (PMID 36694633, 2023). "ALDH1A3 has been shown to initiate breast cancer cell metastasis in the brain; therefore, targeting ALDH1A3 therapeutically was suggested to improve breast cancer patient survival." (PMID 37511575, 2023). "More importantly, ALDH1A3 is positively correlated with breast cancer subtypes, tumor grade, and metastasis." (PMID 36694633, 2023). "Some specificity for ALDH1A3 was observed in citral, where μM concentrations inhibited Aldefluor-mediated ALDH1A3 activity in breast cancer cells and encapsulated citral inhibited ALDH1A3-mediated breast tumor growth." (PMID 36672441, 2023). "In contrast, in vitro studies using ALDH1A3-silenced breast cancer cell lines showed increased migratory capacity along with decreased colony/metastasis formation capacity supporting the data presented in this study." (PMID 38124067, 2023). "The increased invasion/metastatic potential imparted by ALDH1A3 on breast cancer cells appears connected to decreased migration." (PMID 36672441, 2023). "For breast cancer, increased ALDH1A3 results in increased transwell invasion of TNBC MDA-MB-231 cells." (PMID 36672441, 2023). "published that the knockdown of ALDH1A3 robustly reduces ALDEFLOUR activity in breast cancer cells and tumors." (PMID 36694633, 2023). "ALDH1A3 is higher in triple-negative breast cancer (TNBCs), which is an aggressive subtype of breast cancer." (PMID 36672441, 2023). "The gene-metabolite network analyses placed GABA metabolism as a central component of the ALDH1A3-high phenotype in the breast cancer cells." (PMID 34989902, 2022). "The increased expression of the breast cancer stem cell (CSC) marker ALDH1A3 in PDSs from high grade breast cancers is also in line with several earlier studies done in tumor tissue." (PMID 35565301, 2022). "Aldehyde dehydrogenase 1A3 (ALDH1A3) is a cancer stem cell (CSC) marker and in breast cancer it is associated with triple-negative/basal-like subtypes and aggressive disease." (PMID 34989902, 2022). "Together the metabolite profiling, in vivo data, and patient tumor analyses, suggests that GABA is pro-metastatic in breast cancer and GABA metabolism and the signaling pathway is connected to ALDH1A3 in breast cancer cells." (PMID 34989902, 2022). "Patients with late-stage (stage III–IV) breast cancer with high PKCλ, c-Met, and ALDH1A3 levels showed a poorer prognosis than patients with low PKCλ, c-Met, and ALDH1A3 levels." (PMID 36358843, 2022). "The increased systemic GABA or ALDH1A3 levels increased the permissiveness of the breast cancer cells to metastasize to the brain." (PMID 34989902, 2022). "High ALDH activity (due to ALDH1A3 isoform activity) is a defining feature of breast cancer stem cell (CSC) populations." (PMID 34989902, 2022). "Determine how ALDH1A3 alters the metabolite profile in breast cancer cells and assess potential impacts." (PMID 34989902, 2022). "ALDH1A1 and ALDH1A3 can dramatically enhance ALDH1 activity and are associated with a poor prognosis in patients with breast cancer." (PMID 36387165, 2022). "Several studies have confirmed the critical role of ALDH1A3 in increasing metastatic behavior and cancer stemness in several cancer types, including breast cancer, lung cancer, colon cancer, glioblastoma, and cholangiocarcinoma." (PMID 34440089, 2021). "In breast cancer, the citral reduces the growth of breast cancer tumors by inhibiting the breast stem cell marker ALDH1A3." (PMID 34670872, 2021). "High expression of ALDH1A3 predicts poor prognosis in glioma, melanoma, glioblastoma, and breast cancer." (PMID 32612951, 2020). "Our results also show that ALDH1A3 is overexpressed in breast cancer cell lines of different subtypes." (PMID 32423137, 2020).
breast carcinoma (continued). "Here we report that PKCλ expression was enriched in basal-like breast cancer, among breast cancer subtypes, and was correlated with ALDH1A3 expression (p = 0.016, χ2-test)." (PMID 32658903, 2020). "To mechanistically investigate this relationship further, we treated a panel of breast cancer cell lines with the ALDH1A3 product all-trans retinoic acid (ATRA), a nuclear receptor ligand and gene expression induction molecule." (PMID 31197235, 2020). "ALDH1A3 is an important contributor to Aldefluor activity in breast cancer and its expression is predictive of metastasis." (PMID 30622340, 2019). "For example, liver cancer and kidney cancer show high level of ALDH1A1, whereas breast cancer, ovary cancer, skin cancer, pancreatic cancer, and esophagus cancer express higher level of ALDH1A3." (PMID 30220009, 2019). "A recent study showed that the majority of small-sized Ki-67+ proliferating progenitors within human HCC1937 breast cancer cells selectively express high levels of ALDH1A3." (PMID 30733805, 2019). "The opposing tumor growth effects of ALDH1A3/RA in breast cancer cells depend upon differential gene expression induced by ALDH1A3 or RA in MDA-MB-231 and MDA-MB-468 cells." (PMID 31590252, 2019). "Among these, ALDH1A3 reportedly contributes significantly to ALDH1 activity in breast cancer cells, and its expression correlates significantly with tumor grade in breast tumor patients." (PMID 30559934, 2018). "In breast cancer, ALDH1A3 reportedly contributes significantly to ALDH1 activity, and its expression correlates significantly with cancer type, tumor grade and metastasis." (PMID 30559934, 2018). "High expression of c-Met correlated with the expression of ALDH1A3 in Basal-like type of breast cancer." (PMID 28966724, 2017). "We next assessed the influence of ALDH1A1 and ALDH1A3 knockdown on breast cancer cell adhesion and migration in vitro." (PMID 28937653, 2017). "This study characterizes the transcriptional response of MDA-MB-231 and MDA-MB-468 breast cancer cells to retinaldehyde dehydrogenase 1A3 (ALDH1A3) and all-trans retinoic acid (atRA)." (PMID 29192143, 2017). "Malignant breast cancer cell behavior in vitro was assessed in response to direct knockdown of ALDH1A1 or ALDH1A3 by siRNA." (PMID 28937653, 2017). "In this study, we showed that high expression of c-Met correlated with the expression of ALDH1A3 in Basal-like type of breast cancer." (PMID 28966724, 2017). "In this study, we show that high expression of c-Met correlates with the expression of ALDH1A3 in breast cancer." (PMID 28966724, 2017). "Particularly, isoform ALDH1A3 has been reported to contribute significantly to ALDH1 activity in breast cancer cells and its expression significantly correlates with cancer type, tumor grade and metastasis in breast tumor patients." (PMID 28966724, 2017). "More recent work by this group led to the observation that overexpression of ALDH1A3 in MDA-MB-231 human breast cancer cells increases in vitro invasion and in vivo primary tumor growth and lung metastasis in mice, likely due to changes in RA signaling." (PMID 28937653, 2017). "ALDH1A3 has been observed to be involved in metastasis in vivo in breast cancer after cancer cell xenotransplantation into mouse models." (PMID 26445849, 2016). "For example, ALDH1A1 and ALDH1A3 have been shown to play functional roles in lung and breast cancer cell migration and invasion, although the mechanisms underlying this behavior have not been established." (PMID 26445849, 2016). "We also evaluated the association between ALDH1A3 gene expression and TNBC prognosis because one study had suggested that ALDH1A3 expression can predict metastasis in breast cancer patients." (PMID 26462023, 2015). "Cluster I showed overexpression of the lncRNAs that influence their neighboring genes, ALDH1A3 (a breast cancer stem cell marker), SOX4, SOX9, and VIM." (PMID 25296969, 2014).